HSPA8 (heat shock protein family A (Hsp70) member 8)
Diseases named in the same sentence as HSPA8 in open-access papers (continued):
Sharing a sentence is not in itself a finding about the gene and the disease.
cancer (continued). "Three different siRNAs or siRNA pools each for HSPA1A/HSPA1B and HSPA8 and, in addition, siRNA pools against HSPA2, which is expressed in a tissue specific manner and was implicated in cancer cell survival, and HSPA5 were utilized." (PMID 24265689, 2013). "IL-6, EGFR and HSPA8 act as survival factors for neoplasm and increased circulating levels of these proteins have been observed in various types of cancer patients." (PMID 23414419, 2013). "HSPA8 expression was modestly down-regulated in both cancer cell lines compared to MCF10A cells." (PMID 41399382, 2026). "Pan-cancer analysis revealed the oncogenic nature of HSPA8 in a majority of tumors, including BC." (PMID 38057779, 2023). "HSPA8 plays an important role in regulating the activity and autophagy of cancer cells." (PMID 36452344, 2022). "Decreased expression of HSPA8 is beneficial for suppressing the proliferation of cancer cells, inducing cell proliferation arrest, and acting as a modulator of viability and autophagy for cancer cells." (PMID 33926391, 2021). "Besides, the high HSPA1A, HSPA1B, HSPA4, HSPA5, HSPA8, HSPA13, and HSPA14 expressions were inversely associated with the overall survival rate of patients, tumor grade, and cancer stage." (PMID 34059060, 2021). "We focused on the detailed mechanisms of OC and OC_biotin in regulating HSPA8 in cancer cells." (PMID 33390942, 2020). "Considering that HSP70 is highly expressed in various cancer cells, we examined whether OC still affects cell apoptosis following HSPA8 knockdown by small interfering RNA (siRNA) or overexpression by plasmid." (PMID 33390942, 2020). "Furthermore, we found that OC inhibited HSPA8 nuclear translocation in cancer cells, which then suppressed the protective effects of HSPA8 under certain stresses." (PMID 33390942, 2020). "Molecular chaperones HSP90α (HSP90AA1) and HSC70 (HSPA8) could assist the stability and function of many oncogenic proteins then keep cancer cells surviving." (PMID 33246450, 2020). "We assume that HSPA8 may be expressed by other stromal cells and be an intermediate link responding to changing environmental pressures during the cancer evolution and activating the glycolysis reaction, and further study will be needed." (PMID 32635458, 2020). "HspA8 is overexpressed in cancer cells and it belongs to the Hsp70 family." (PMID 31921692, 2019). "HSPA8 and other HSPs, are extraordinarily abundant in the cell membrane proteome of cancer cells." (PMID 28934328, 2017). "Additionally, HSPA8 is a member of the heat-shock protein 70 families and known to promote cancer cell growth." (PMID 23414419, 2013). "Given that HSPA8 are induced by many different stress signals to promote cell survival in adverse pathological conditions, such as cancers, perhaps, anticancer therapy by targeting HSPA8 in GBM1 may be an option as well." (PMID 23875172, 2013). "For instance, HSPA8 supports the assembly and activity of the cyclin D1 holoenzyme by binding and folding freshly generated cyclin D1, and cyclin D1 is amplified and overexpressed in a variety of malignancies, where it speeds up the proliferation of cancer cells." (PMID 37771276, 2023). "In summary, macrophages could induce the activation of DLL3-dependent Notch1/Notch2 signaling, the upregulation of IL-33, and the degradation LG3BP and HSPA8, resulting in enhanced cancer-cell proliferation and elevated IL-1β, IL-12, and IL-10 secretion by macrophages." (PMID 35382168, 2022). "Furthermore, we showed that OC regulates the function of HSPA8 in several cancer cell lines." (PMID 33390942, 2020). "In cancers where HSPA4 expression significantly impacts prognosis, four genes—HSP90AA1, HSPA8, DNAJB1, and HSP90AB1—demonstrated a pronounced correlation." (PMID 38305786, 2024). "The HSP70s family includes constitutively expressed members HSC70 (HSPA8) and stress-inducible member HSP70 (HSPA1A/HSPA1B), which have been demonstrated to control protein maturation and proper folding in cancer cells." (PMID 36773708, 2023).
cancer (continued). "Networks of HSP70 or HSP90 (including HSPA8, HSPA5, and HSP90B1) play important roles in the regulation of energy metabolism as well as in cancer cells’ oncogenesis and malignant progression." (PMID 36038612, 2022). "This activation enhanced the proliferation and migration of cancer cells, and facilitated the expression of IL-33 cytokine by DLL3 and the degradation of LG3BP and HSPA8." (PMID 35382168, 2022). "TUBA1C (r was range from 0.29 to 0.66), TUBA1B (0.21~0.65), P4HA1 (0.25~0.74), HSPA8 (0.17~0.60), CCNB1 (0.22~0.62) as the top five genes were highly correlated with glycolysis score across cancers." (PMID 32635458, 2020). "The different expression of HSPA8 and P4HA1 was observed in cancer cell lines and tumor fragments of multiple cancer types under hypoxia compared with normoxic conditions from previous studies (GEO numbers see Methods)." (PMID 32635458, 2020). "In cancer cells IC50 value of VER was the highest for NCI-H520 cells, which expressed HSPA1, HSPA2 and HSPA8 proteins at low levels in comparison to other NSCLC cell lines in our model." (PMID 31591429, 2019). "We found that for significant reduction of viability of cancer cells simultaneous knockdown of heat-inducible Hsp70 (HSPA1) and constitutive Hsc70 (HSPA8) is necessary." (PMID 24265689, 2013). "Crucially, upon evaluating genes that may significantly influence cancer prognosis, HSP90AA1, HSPA8, DNAJB1, and HSP90AB1 manifested pronounced correlations with HSPA4 expression." (PMID 38305786, 2024). "Together, these experiments indicate a paracrine-positive feedback circuit in cancer in which TAMs induce tumor-cell Notch-dependent secretion of cytokines, and this induction may also take effect through the degradation of LG3BP and HSPA8." (PMID 35382168, 2022). "The genes ITGA3, HSPA8, CTSD, ATG12, CLN3, ATG7, and MAP1LC3C negatively influenced patient survival, whereas WIPI1 may protect the patients from cancer-related death." (PMID 35186475, 2022). "At present, related studies have shown that HSPA8 is a new cancer biomarker, but the expression of HSPA8 in human TNBC is not clear." (PMID 36452344, 2022). "Our transcriptome data showing decreased expression of HSPA8 and increased expression of TXNIP upon treatment with synthetic rocaglates further support the previously suggested fundamental link between anabolic and catabolic processes in cancer cells." (PMID 34546000, 2021). "On the contrary, other reports show that only the simultaneous inhibition of several HSPA paralogs (including HSPA8), but not a paralog-selective reduction in the level of any of them, had anti-proliferative or cytotoxic effects in cancer cells." (PMID 32987811, 2020). "CNV-TFs TBP and NFYB targeted HSPA2, HSPA8 and HSPA1A respectively, three members of heat shock protein 70 which could inhibit apoptosis in cancer cells through simultaneous and independent mechanisms." (PMID 24897108, 2014). "At present, we do not know whether the interaction of TLQP-21 and HSPA8 that we have unveiled in SH-SY5Y is of relevance to cancer cells alone or to healthy cells, too." (PMID 28934328, 2017). "Similarly, down-regulation of the constitutively expressed Hsc70 (HSPA8) to the level achieved here (ca. 40% of its steady-state level) did not compromise viability of the cancer cells." (PMID 24265689, 2013). "Moreover, several other molecular chaperones like HSP90A/HSP90 or HSPA8/HSC70 also immunoprecipitated with this complex suggesting the existence of chaperone networks involved in sequestration of TAp73α, thus allowing cancer cells to survive in the presence of chemotherapeutics." (PMID 29137250, 2017).
tumor (105 papers, 2003 to 2026). "Specifically, previous studies have demonstrated that HSPA8 is associated with tumor metastasis and recurrence in HCC." (PMID 36768989, 2023). "In adenomatous lesions obtained from the same tumor with a carcinomatous lesion, we identified pairs of miRNA-130a-3p/HSPA8 and miRNA-22-3p/RP53 that were linked to multiple pathways." (PMID 35875068, 2022). "Furthermore, NDRG1 can mitigate Erastin-induced ferroptosis and promote tumor progression, with eight genes, including HSPA8 and CDH1, potentially being part of its underlying molecular mechanisms." (PMID 40386780, 2025). "Additionally, it has been shown that the upregulation of HSPA8/HSC70 is associated with poor prognosis in patients with multiple cancers and stimulates tumor immune responses or drug resistance." (PMID 36008860, 2022). "SERPINA1, MAP1LC3A, DIRAS3 were down-regulated in a high risk group and up-regulated in a low risk group, which were potentially tumor suppressor genes; HSPA8, HSPB8 were up-regulated in a high risk group and down-regulated in a low risk group, which were probably promoting oncogenes." (PMID 34876005, 2021). "This identified P4HA1 and HSPA8 as candidate factors underlying gene expression differences in glycolysis-high and -low tumor cells and in other TME stromal cells, respectively, seemed responsible for tumor-specific cell glycolysis phenotypes in hypoxia microenvironment." (PMID 32635458, 2020). "Altogether, the aberrantly expressed signature genes (XRCC4, CTSL, CTSD, and HSPA8) is closely related to tumor malignant progression." (PMID 41399382, 2026). "Correlation analysis identified key splicing factors, including HSPA8, SNRPB, and hnRNPs, linked to tumor-specific AS events, especially for reduced intron retention." (PMID 40702779, 2025). "More importantly, the in vivo experiments showed that TNBC tumor xenografts were less sensitive to pristimerin when HSPA8 expression was downregulated." (PMID 39813169, 2025). "The WB analysis of proteins extracted from tumour tissues from nude mice revealed a decrease in HSPA8 expression in the group with stable silencing of circRREB1." (PMID 40653497, 2025). "To further evaluate the role of HSPA8 in tumorigenesis and tumor development in CRC, we then evaluated the protein level of HSPA8 in 25 CRC tissues compared to adjacent normal tissues." (PMID 37973552, 2024). "In contrast, HSPA8 knockdown suppressed tumor growth, while was able to restore the effects of RPL35A overexpression." (PMID 38395908, 2024). "Further, an unidentified m/z value (m/z 1461.702) and [MVNHFIAEFK] (m/z 1235.618) from Heat shock cognate 71 kDa protein (HSPA8) were higher in male tumour regions, while two unidentified m/z values (1661.060 and 1305.840) were higher in female stroma regions." (PMID 38492056, 2024). "Further in vivo experiments suggested that RPL35A overexpression significantly accelerated tumor growth in vivo, whereas HSPA8 knockdown significantly slowed tumor growth." (PMID 38395908, 2024). "In HFS, we had identified that HSPA8 was highly expressed, which had also been founded in the tumor as exomere." (PMID 36684113, 2023). "HSPA8, one of the HCs, was chosen as the subject of an investigation to the processes of tumor metastasis." (PMID 38057779, 2023). "In order to investigate the impact of HCs on tumor cells, we specifically chose the HSPA8 to examine its potential tumorigenic effect." (PMID 38057779, 2023). "The expressions of LG3BP and HSPA8 were both low in normal tissues but high in parts of tumor samples." (PMID 35382168, 2022). "Previous many scholars believe that HSPA8 is involved in tumor molecular chaperone autophagy and participate in the process of BC through molecular chaperone autophagy." (PMID 36452344, 2022). "In order to elucidate the role of the signature genes’ biological functions, the association of STMN1, RAP1A, FLT3, HSPA8, ANGPT2, and PGF was positively associated with tumor purity in HCC." (PMID 34178637, 2021).
tumor (continued). "Four heat shock proteins (Hspa5, Hsp90ab1, Hspa8 and Hsp90aa1) were included in the top candidate list and Hsp90ab1 was predicted to be one of the most influential tumor suppressors, as well as calreticulin (Calr) and peptidylprolyl isomerase B (Ppib)." (PMID 33859739, 2021). "HSPA8 has been reported have to anti-tumor effects by inducing chemokine production from tumor cells and activation of chemo-attracted dendritic cells via the TLR4 pathway in mice." (PMID 30918657, 2019). "Simultaneous ttargeting of HSPA8 and HSP1Ainducestumor-specific apoptosis, which highlights the important role of HSPA8 in viability of tumor cells." (PMID 28934328, 2017). "We examined growth and immune signalling proteins such as EGFR, HSPA8 and cytokines IL-6 that are involved in the survival of tumor." (PMID 23414419, 2013). "Interestingly, HSPA8 and an unidentified m/z value (m/z 1461.702) localised to tumours specific to males, and 2 unidentified m/z values (m/z 1305.840 and 1661.060) localised to stroma, that were specific to females." (PMID 38492056, 2024). "Importantly, the reduced tumour size and increased Fe2+, PTGS2, and 4HNE levels caused by LACTB overexpression were significantly rescued by HSPA8 overexpression." (PMID 39047638, 2024). "Additionally, HSPA8 has been reported to be highly immunogenic and overexpressed in several tumor cells, which indicates its close relationship with tumors." (PMID 36768989, 2023). "Furthermore, our in vitro experiments yielded evidence indicating that HSPA8 functions as an oncogenic gene, facilitating tumor metastasis and invasion." (PMID 38057779, 2023). "Furthermore, we summarized that the risk score is strongly related to tumor recurrence in BRCA database (p = 0.01), but only HSPA8 and PRKDC performed remarkable expression difference in the recurrent tumor and primary tumor (NS, p < 0.01)." (PMID 37051596, 2023). "Interestingly, DNAJC12, a gene strongly upregulated in Luminal A and B tumours, was found to interact with HSPA8 under ERSR." (PMID 29954368, 2018). "Furthermore, P276-00 inhibited expression of soluble proteins such as IL-6, EGFR and HSPA8 that promote tumor microenvironment." (PMID 23414419, 2013). "In addition, studies showed that HSPA8 was a key molecular regulator of chaperone-mediated autophagy, we should further explore whether RPL35A regulates autophagy through HSPA8 and thus plays a tumor-promoting role in the progression of CCA." (PMID 38395908, 2024). "Similarly, HSPA4, HSPA8, HSPA9, and HSPA12B are associated with tumor occurrence and development." (PMID 34059060, 2021). "Given that HSPA8 is an chaperone by protection of the proteome from stress and the expression of HSPA8 is highly expressed in tumor tissue, we assume it may play a critical role in mediating glycolysis coping with hypoxia pressure in tumor evolution." (PMID 32635458, 2020). "Western blot analysis confirmed that ES treatment elevated the levels of Histone H4, Hspa8, MSN, Eef2, Aldoa, and Eno1, which is consistent with previous studies demonstrating Eno1’s tumor-suppressive function." (PMID 39940798, 2025). "Heat shock proteins, particularly HSPA8 (found in both patient groups), as well as HSPA1B and HSPA1L, were found in LRPCa, reflecting the role of the HSP70 family in tumor cell survival." (PMID 40136513, 2025). "Demonstrated as potent enhancers of tumor and cellular survival in cellular stress, the upregulation of the epichaperome genes HSP90AA1, HSPH1, and HSPA8 promotes the equilibrium of radio- and chemoresistance seen in tumor and indirect cell dormancy." (PMID 38994941, 2024). "Cell experiments and subcutaneous tumorigenesis experiments in nude mice were performed to evaluate the effects of RPL35A and HSPA8 on the proliferation, apoptosis, cell cycle, migration of CCA cells and tumor growth in vivo." (PMID 38395908, 2024). "In conclusion, the histone chaperones HSPA8 and DEK are closely related to the tumor immunity of HCC." (PMID 36768989, 2023).
tumor (continued). "The results showed that the expression of PRMT9, HSPA8, and GPX4 were significantly higher in tumor than that in adjacent tissues." (PMID 37715221, 2023). "In the current study, we revealed that the histone chaperones HSPA8 and DEK strongly influence the tumor immunity of HCC." (PMID 36768989, 2023). "Further analysis of the shared 61 proteins revealed that there were a large number of tumor-related proteins, such as HSPA5, HNRNPH1, HSPA8, TGM3, and SERPINB12." (PMID 37715221, 2023). "Although the current study reveals the effect of the histone chaperones HSPA8 and DEK on tumor immunity in HCC, it has certain limitations and drawbacks." (PMID 36768989, 2023). "Whereas JUN, HSPH1, HSPA8, HSPA6, HSP90AB1, and EGR1 were found to be the DEGs in both Tumor vs. normal and tumor vs. metastasis group." (PMID 37335089, 2023). "We suggest that the mRNA/miRNA pairs HSPA8/miRNA-130a-3p and RP53/miRNA-3907 or miRNA22-3p play an important role in the development of the adenomatous component of a tumor." (PMID 35875068, 2022). "And HSPA8 is the key protein of CMA pathway, so it can indirectly indicate that CMA activity is higher in tumor tissue." (PMID 36452344, 2022). "Surprisingly, HSPA8/HSC70 siRNA transfection drastically decreased the migration and invasion of K150 and E109 cells induced by exogenous DJ-1 in transwell and 3D tumor spheroid invasion assays." (PMID 36008860, 2022). "In adenomatous lesions isolated from the same tumor, we observed two inverse correlations of paired mRNAs/miRNAs, including RP53/miRNA-3907 or miRNA22-3p and HSPA8/miRNA-130a-3p." (PMID 35875068, 2022). "Consistent with our results in TCGA, HSPA9 and HSPA8 were significantly upregulated in CRC tissues compared with normal tissues, and mainly localized to the cell membrane and cytoplasm in the tumor cells." (PMID 35711437, 2022). "All cases with at least four evaluable cores per tumor were used for assessment of heterogeneity of marker expression throughout the tumor, resulting in 197 cases for LAMP2A and 196 cases for HSPA8." (PMID 34685711, 2021). "It was also seen that P276-00 treatment reduced expression of tumor micro-environment proteins such as IL-6, secreted EGFR and HSPA8." (PMID 23414419, 2013). "The up-regulated genes following treatment included heat shock family proteins such as HSP90AA1, HSPA8, DNAJB12, HSPA1L, DNAJA1, HSPA4L, consistently with other array studies in different tumor cell types." (PMID 20920318, 2010). "Furthermore, western blot also confirmed the aberrant expression of CTSL, CTSD, HSPA8, and XRCC4 in tumor tissues relative to paracancerous normal tissues." (PMID 41399382, 2026). "Moreover, we analyzed the functions and potential pathways of crucial genes related to CLDN12 expression, including HSPA8 and HIF-1α, in the process of tumor progression." (PMID 41461671, 2025). "Immunohistochemical staining detected the protein level of Ki67 in tumor tissues, and found overexpression of RPL35A upregulated Ki67 protein, and knockdown of HSPA8 downregulated Ki67 protein, which was consistent with the change trend of cell proliferation in vitro." (PMID 38395908, 2024). "In vivo, HSPA8 downregulation also inhibited tumor growth and decreased Ki-67 protein expression in tumor tissues, which was opposite to the effect of RPL35A overexpression on tumor growth." (PMID 38395908, 2024). "CASP3, SRC, ESR1, JAK2, PRKACA, HSPA8 and CAT exhibited stronger interactions with other factors, suggesting that they may be the key targets for tumor treatment." (PMID 38675723, 2024). "Both antibodies do not cross-react with the constitutive form Hsc70 (HSPA8) or other chaperones as determined by Western blot analysis of tumor cell lysates and by dot blot analysis using Hsp27, Hsp60, and Hsp90 as recombinant proteins." (PMID 36399258, 2023).